TLR6 (toll like receptor 6)
Diseases named in the same sentence as TLR6 in open-access papers (continued):
Sharing a sentence is not in itself a finding about the gene and the disease.
pulmonary TB (4 papers, 2011 to 2023). "TLR6 variant was documented to contribute to human susceptibility to TB and was up-regulated in fresh unstimulated whole blood of patients with active pulmonary TB (n = 10) compared with healthy donors." (PMID 21904626, 2011). "We carried out a case–control association community based study, genotyping 12 polymorphisms of TLR2, TLR4, TLR6 and TLR9 genes in 90 patients with confirmed pulmonary TB and 90 unrelated exposed but asymptomatic household contacts." (PMID 24053111, 2013). "Therefore, we examined whether polymorphisms in TLR2, TLR4, TLR6 and TLR9 are associated with the susceptibility to pulmonary TB in Mexican individuals from a rural area with high incidence of TB." (PMID 24053111, 2013).
atopic asthma (3 papers, 2013 to 2017). An asthma that is characterized by symptoms that are triggered by an allergic reaction caused by inhaled allergens such as dust mite allergen, pet dander, pollen and mold. "In a large German study, a protective effect of genetic variants on atopic asthma was identified in the TLR2-associated heterodimer network consisting of TLR1, TLR6, and TLR1012." (PMID 28592890, 2017).
atopic eczema (3 papers, 2005 to 2017). A common chronic pruritic inflammatory skin disease with a strong genetic component. "Interestingly, the finding was robust to adjustment with atopic eczema, which suggests that the association between TLR6 and bronchial hyper-reactivity is not dependent on atopy." (PMID 26741133, 2016).
bronchiolitis (3 papers, 2016 to 2017). Inflammation of the bronchioles characterized by swelling of the bronchioles and mucus accumulation. "We have earlier studied the TLR1rs5743618, TLR2 rs5743708, TLR3 rs3775291, TLR4 rs4986790 and TLR6 rs5743810 polymorphisms, and reported their associations with bronchiolitis and post-bronchiolitis outcomes." (PMID 27498757, 2016). "This suggests that wild TLR2 subfamily genotypes may even be protective for later airway hyper-reactivity, and, in particular, TLR6 rs5743810 variant genotypes may be associated with increased airway reactivity after infant bronchiolitis." (PMID 26741133, 2016). "Presence of TLR6 rs5743810 genotypes (wild vs. variant) and baseline IOS (z-scores) and exercise-induced changes (z-scores) in the 98 former bronchiolitis patients." (PMID 26741133, 2016). "Among the nine studied TLRs, only TLR7 rs179008 showed some exploratory associations with post-bronchiolitis lung function deficiency, and polymorphisms of TLR4 rs4986790, and TLR6 rs5743810 in particular, with airway reactivity." (PMID 26741133, 2016). "The joint analyses of the TLR1 rs5743618, TLR2 rs5743708, TLR6 rs5743810 and TLR10 rs4129009 genotype combinations and baseline (z-scores) and hyper-reactivity IOS measurements (Δz-scores) in 97 children hospitalized for bronchiolitis." (PMID 26741133, 2016).
coronary artery disease (3 papers, 2013 to 2016). "Here we investigated the association of the TLR-6 SNP Pro249Ser (rs5743810) with susceptibility to atherogenesis in two independent patient groups with proven coronary artery disease by comparison with age-matched healthy control groups." (PMID 24498948, 2013). "Given that coronary artery disease is the major cause of death in the Western world, we speculated that this protective Ser249Ser TLR-6 genotype would be overrepresented in an elderly cohort of healthy controls in comparison to a young healthy control group, where due to age CAD doesn’t play a role." (PMID 24498948, 2013).
glioma (3 papers, 2019 to 2023). A benign or malignant brain and spinal cord tumor that arises from glial cells (astrocytes, oligodendrocytes, ependymal cells). "Interestingly, CCLE data consistently indicated that the TLR6 gene signature in U87‐MG cells was actually common throughout all glioma cell lines." (PMID 31282108, 2019). "In glioma, elevated TLR1, TLR2, TLR4, TLR5, TLR6, and TLR9 expressions were observed in tumor cell lines and tissues compared with non-neoplastic brain tissues, particularly in the mesenchymal subtype of GBM." (PMID 34715891, 2021). "Up to date, TLR2, TLR3, TLR4, TLR7, and TLR9 have been intensely studied in glioma, while less or missing information is available regarding the mechanisms of TLR1/TLR6 (dimerizes with TLR2), TLR5, TLR8 (dimerizes with TLR7), and particularly TLR10." (PMID 34715891, 2021).
Lewis lung carcinoma (3 papers, 2010 to 2016). "Lewis lung carcinoma (LLC) activated macrophage to produce IL-6 and TNF-а through activation of TLR2 and TLR6." (PMID 27336891, 2016). "By activating TLR2:TLR6 complexes and inducing TNF-α secretion in myeloid cells, versican strongly enhances Lewis lung carcinoma metastatic growth." (PMID 20145615, 2010).
lung carcinoma (3 papers, 2013 to 2025). "The activated TLR2 : TLR6 can induce TNF-alpha secretion by myeloid cells and enhance lung cancer bone metastasis growth." (PMID 36440359, 2022).
abscesses (2 papers, 2017 to 2020). "Polymorphisms in TLR1 and TLR6 influence the severity of cSSSIs as assessed by the lesion size of major abscesses and DFIs." (PMID 31786695, 2020). "In patients with large abscesses, hetero- or homozygosity for the allelic variant TLR6 (P249S) was associated with significantly smaller lesions while homozygosity for the allelic variant TLR1 (R80T) was associated with significantly larger lesions." (PMID 31786695, 2020). "Patients hetero- or homozygous for the allelic variant TLR6 P249S had smaller abscess lesions at clinical presentation and patients homozygous for the allelic variant TLR1 R80T had larger abscess lesions." (PMID 31786695, 2020). "In conclusion, this study showed that polymorphism TLR6 P249S plays a protective role, in contrast to polymorphism TLR1 R80T, in the severity of major abscesses, defined as lesion size at clinical presentation." (PMID 31786695, 2020). "In addition, cryptic abscesses and mucosal edema was more frequently observed in the colons of TLR1−/− and TLR2−/− mice than in those of TLR6−/− and wild-type C. albicans and DSS-treated mice." (PMID 28289440, 2017).
acute lymphoblastic leukemia (2 papers, 2014 to 2022). Leukemia with an acute onset, characterized by the presence of lymphoblasts in the bone marrow and the peripheral blood. "Our study demonstrated that TLR6 C > T rs5743810 and TLR9 C > T rs5743836 polymorphisms are associated with the risk of acute lymphoblastic leukemia and TLR1 T > G rs5743618 and TLR9 C > T rs5743810 is involved with death." (PMID 36071076, 2022). "In our study, TLR6 C > T rs5743810 and TLR9 C > T r5743836 polymorphisms seem to be a risk for developing acute lymphoblastic leukemia." (PMID 36071076, 2022). "In acute lymphoblastic leukemia (ALL) cell lines, TLR1, TLR2, TLR3, TLR4, TLR6 and TLR7 are expressed albeit at variable levels." (PMID 25112836, 2014).
aspergillosis (2 papers, 2012 to 2017). Aspergillosis is an infection, growth, or allergic response caused by the Aspergillus fungus. "In single studies the TLR6 Ser249Pro SNP has been linked with susceptibility to infection with aspergillosis and women homozygous for the 249Ser allele were found to have thinner left ventricular posterior walls as well as possessing monocytes responding weakly to the TLR6 ligand zymosan." (PMID 23730203, 2012). "Of note, several polymorphisms of human TLRs, e.g., TLR1, TLR2, TLR4, TLR6, or TLR9, have been associated with increased risk of invassive aspergillosis in susceptible hosts." (PMID 29081774, 2017).
astrocytoma (2 papers, 2018 to 2023). "This study aims to analyze the expression levels of plasmatic cell membrane TLRs (TLR1, TLR2, TLR4, TLR5, and TLR6) in human astrocytomas the most prevalent tumors of CNS different grades (II-IV)." (PMID 29912993, 2018). "TLR1, TLR2, TLR4, TLR5, and TLR6 are involved in a diversity of cellular responses, ranging from cell proliferation to cell death, and as such they are the targets of the current study in astrocytomas." (PMID 29912993, 2018). "In this regard, experimental evidence on the increased cell surface expression of TLR1, TLR2, TLR4, TLR5, and TLR6 in astrocytoma samples compared to non-neoplastic brain tissues clearly revealed the involvement of these TLRs in the progression of astrocytoma." (PMID 37822929, 2023). "In the present study, higher expression levels of TLR1, TLR2, TLR4, TLR5, and TLR6 were demonstrated in human diffusely infiltrating astrocytomas (grades II to IV) in comparison to non-neoplastic brain tissue." (PMID 29912993, 2018). "In summary, increased cell membrane TLR1, TLR2, TLR4, TLR5, and TLR6 expressions were demonstrated in astrocytomas compared to non-neoplastic brain tissue, mostly in GBM group, and particularly in the mesenchymal subtype." (PMID 29912993, 2018).
candidiasis (2 papers, 2010 to 2020). Infection with the organism Candida. "A recent study demonstrated that a wild-type strain of Candida induced TLR2, TLR4, TLR6, and TLR9 gene expression activation in the epithelial cells showing that different receptors may play important roles in candidiasis." (PMID 32466609, 2020).
childhood asthma (2 papers, 2013 to 2020). "Toll-like receptor 2, toll-like receptor 6, toll-like receptor 9, and toll-like receptor 10 appear to have some association with childhood asthma in Caucasians." (PMID 23496969, 2013).
colon cancer (2 papers, 2021 to 2023). "TLR6 expression was previously reported to be significantly lower in colon cancer than normal colon tissue, which is consistent with the idea that TLR6 signaling exerts an inhibitory effect on carcinogenesis." (PMID 37232814, 2023). "TLR6 is suggested to have an anticancer function, as described in the literature for colon cancer." (PMID 33917061, 2021).
dengue (2 papers, 2015 to 2022). "Altogether, these results indicate that TLR2/TLR6/CD14- mediated sensing of immature dengue particles induces the production of TNF-α and IL-1β by monocytes." (PMID 36240261, 2022). "Among those that responded, DV2-infected wild-type mice secreted higher amount of IL-6 compared to that of the DV2-infected TLR6-/- mice, indicating that TLR6 activation contributed to the IL-6 expression during dengue virus infection." (PMID 26226614, 2015). "In order to determine if TLR6 activation during dengue virus infection contributes to the pathogenesis of the disease, wild-type and TLR6-/- mice were injected with 2.7 x 108 PFU of DV2 on day 1–2 day-old." (PMID 26226614, 2015). "Blocking of TLR2 and TLR6 also reduced the amount of IL-6 produced by PBMC during dengue virus infection, this suggested that TLR2 and TLR6 are activated during dengue virus infection and this activation led to increase in IL-6 secretion." (PMID 26226614, 2015). "Upon dengue virus infection, higher percentages of TLR6+CD14+ cell population was observed compared to the mock-infected PBMC on day 2 and 3 post-infection." (PMID 26226614, 2015). "Our study provides new insights into the involvement of TLR6 in dengue virus infection and the potential of using TLR6 anatagonist in therapeutic treatment for DV infection." (PMID 26226614, 2015). "TLR6-targeted therapies have a potential for intervention in dengue virus infection and amelioration of disease symptoms." (PMID 26226614, 2015). "In our previous study, several genes involved in the TLR6 pathway have been found to be significantly up-regulated during dengue virus infection in K562 cells on day 3 post-infection which include TLR6, IL-6, TNF-α and CD80." (PMID 26226614, 2015). "In addition, the interaction of viral factor with TLR6 was found to play an important role in the manifestation of dengue virus infection." (PMID 26226614, 2015). "This up-regulation suggested the possible involvement of TLR2 and TLR6 in dengue virus infection." (PMID 26226614, 2015). "As TLR2 is partner of TLR6, its expression by PBMC during dengue virus infection was also investigated." (PMID 26226614, 2015). "In the current study, dengue virus infection was found to activate and up-regulate TLR2 and TLR6 of human PBMC and DV NS1 protein was shown to be the viral protein responsible." (PMID 26226614, 2015). "Hence, TLR6 may play an important role in the immunopathogenesis of dengue virus infection." (PMID 26226614, 2015). "Among those that responded, DV2-infected wild-type mice secreted higher amount of TNF-α compared to that of the DV2-infected TLR6-/- mice, indicating that TLR6 activation contributed to the TNF-α expression during dengue virus infection." (PMID 26226614, 2015).
emphysema (2 papers, 2013 to 2014). "We have previously shown that CD56+ cells express TLRs and that the percentage of lung NK cells expressing TLR5, TLR6, and TLR2/1 correlated with worsening emphysema as determined by computed tomography quantification." (PMID 25078269, 2014). "Similarly, NK cells expressing TLR5, TLR6, and TLR2/1 also correlated with worsening emphysema as determined by CT quantification." (PMID 23374856, 2013).
endometritis (2 papers, 2014 to 2017). An acute or chronic, usually bacterial infectious process affecting the endometrium. "The ability of endometrial cells to detect and respond to bacterial lipopeptides via TLR2/TLR1 and TLR2/TLR6 is probably important for the onset and persistence of endometritis in cattle." (PMID 24437488, 2014).
esophageal squamous cell carcinoma (2 papers, 2023 to 2025). Esophageal squamous cell carcinoma (ESCC) is a type of esophageal carcinoma (EC) that can affect any part of the esophagus, but is usually located in the upper or middle third. "For example, in esophageal cancer, increased expression of TLR3, TLR4, TLR7, and TLR9 has been linked to esophageal squamous cell carcinomas, while TLR1, TLR2, TLR4, and TLR6 are often overexpressed in esophageal adenocarcinoma." (PMID 40109582, 2025).
fungal infection (2 papers, 2014 to 2022). "However, fungal infection is commonly recognized via the TLR2, TLR4 and TLR6 signaling pathways and does not result from the secretion of IFN-I." (PMID 24660033, 2014).
hepatitis C (2 papers, 2011 to 2023). "Finally 6 genes (NCOR2, NR1H3, PPARA, IRF3, MAP2K3, and TLR6) were enriched in 3 immune-related pathways, including toll-like receptor signaling pathway, EB virus infection, and hepatitis C." (PMID 37845378, 2023). "Specific activation of TLR-2 in hepatitis C and homo- or heterodimerization with TLR-1 or TLR-6 has been shown; also, when these are blocked a significant decrease on production of proinflammatory cytokines appears, suggesting that some proteins produced by hepatitis C activate innate immune." (PMID 22114589, 2011).
Liver inflammation (2 papers, 2018 to 2025). "Studies looking at the interaction between TLR2 and TLR6 found that deregulation of TLR6 expression potentiated the TLR2-mediated liver inflammation." (PMID 29563854, 2018). "Liver inflammation, assessed by ALT levels, correlated with platelet- and leukocyte-LGP2, in addition to leukocyte-TLR3, -TLR6, -TLR7, and -RIG-I." (PMID 40825056, 2025).
myocardial ischemia (2 papers, 2018 to 2025). A disorder of cardiac function caused by insufficient blood flow to the muscle tissue of the heart. "Interestingly, post myocardial infarction TLR and IRF gene expression was almost exclusively increased in the infarct zone after myocardial ischemia (Tlr2, Tlr3, Tlr6, Tlr7, Tlr9, Irf3, Irf7)." (PMID 29538462, 2018). "All cardiac cells express Toll-like receptors (TLR) 2–4 and TLR6, with TLR4-bearing cells activated via a TLR4 signal due to oxidative stress and the accumulation of activated complement during myocardial ischemia reperfusion, which triggers the onset and development of an inflammatory response." (PMID 39368019, 2025).
Non-Alcoholic Fatty Liver Disease (2 papers, 2016 to 2024). "Besides the classical proinflammatory pathway, TLR6 represents an interesting target identified in our experiments, which has been suggested to play a role in non-alcoholic fatty liver disease and hepatic inflammation." (PMID 38673735, 2024).
schizophrenia (2 papers, 2021 to 2025). A major psychotic disorder characterized by abnormalities in the perception or expression of reality. "Notably, patients with schizophrenia (SZ) exhibited markedly lower TLR6 expression levels compared to healthy control subjects (HCSs) independent of genotype." (PMID 39940697, 2025). "This suggests a potential dysregulation of TLR6 in individuals with schizophrenia, further supporting the hypothesis that TLR6 may play a role in the immune-related mechanisms underlying the disorder." (PMID 39940697, 2025). "Noticeably, as suggested in our study, CXCL1, TLR6 and OSM have been documented to be targeted genes of DNA methylated modification in other diseases, such as schizophrenia, type 1 diabetes and Richter syndrome." (PMID 34017996, 2021).
allergic asthma (1 paper, 2020). A asthma with a basis in a pathological type I hypersensitivity reaction. "It has been reported that Tlr6−/− mice show exacerbation of fungal-induced allergic asthma because of low levels of IL-23 and IL-17A46." (PMID 33093516, 2020).
Autoimmunity (1 paper, 2017). The occurrence of an immune reaction against the organism's own cells or tissues. "A total five genes (Fes, Aif1, Gata3, Tlr6, Tlr2) were identified as hub genes that are most likely related to the silicone-induced immune response, four of which (Aif1, Gata3, Tlr6, Tlr2) have been associated with autoimmunity as target genes or disease markers." (PMID 29245939, 2017). "A total five genes (Fes, Aif1, Gata3, Tlr6, Tlr2) and nine pathways were identified as central participants in the silicone-induced immune response, most of which are also related to autoimmunity." (PMID 29245939, 2017). "Strikingly, most of these hub genes (Tlr2, Tlr6, Aif1, Gata3) have also been reported to be crucial in autoimmunity development." (PMID 29245939, 2017).
Bartonella infections (1 paper, 2025). "The genotypes at positions 1331 of TLR1, 36 of TLR4, and 2187 of TLR6 significantly affected Bartonella infection, with MDGs of 3.08, 2.33, and 3.22, respectively." (PMID 40678527, 2025). "In this study, we analyzed the polymorphisms in six cell surface TLR genes (TLR1, TLR2, TLR4, TLR5, TLR6, and TLR10) in striped hamsters, aiming to determine their association with Bartonella infections and ectoparasite parasitism, including fleas and gamasid mites." (PMID 40678527, 2025).
bovine tuberculosis (1 paper, 2023). "In significantly enriched GO terms in Abergelle, Arado and Raya cattle, we found TLR6 as an important candidate gene for bovine tuberculosis resistance." (PMID 37600659, 2023).
bronchopulmonary dysplasia (1 paper, 2016). Bronchopulmonary dysplasia is a chronic respiratory disease that results from complications related to lung injury during the treatment of infant acute respiratory distress syndrome in low-birth-weight premature infants or from abnormal lung development in older infants. "A recent article identified a single nucleotide polymorphism in toll-like receptor 6 associated with a decreased risk for Ureaplasma respiratory tract colonization and bronchopulmonary dysplasia in preterm infants." (PMID 27537683, 2016).
brucellosis (1 paper, 2013). Brucellosis is a bacterial infection that spreads from animals to people via unpasteurized dairy products or by exposure to contaminated animal products or infected animals. "In addition, the authors reported that TLR6 (but not TLR2) is required for the in vivo control of the bacteria in the murine model of brucellosis, and that murine DCs lacking TLR2 or TLR6 are unable to produce of TNF-α or IL-12." (PMID 23805193, 2013).